ANGPTL7 (angiopoietin like 7)
Description:
Has a role in the formation and organization of the extracellular matrix. In the eye, it functions as a mediator of dexamethasone-induced matrix deposition in the trabecular meshwork, the tissue responsible for the outflow of the ocular aqueous humor and for the maintenance of intraocular pressure. Is a negative regulator of angiogenesis in the cornea, and plays a major role in maintaining corneal avascularity and transparency.
Synonyms: CDT6; AngX; dJ647M16.1
Tractability: Antibody: UniProt places it where antibodies can reach, with high confidence; its Gene Ontology location is reachable by antibodies, with high confidence; UniProt predicts a signal peptide or a membrane-spanning region.
Gene: Protein-coding gene on chromosome 1 (11,189,355 to 11,195,981, forward strand). Ensembl gene ENSG00000171819.
Subcellular location: Secreted
Gene Ontology:
Molecular function: identical protein binding; protein binding
Biological process: negative regulation of vasculature development involved in avascular cornea development in camera-type eye; regulation of extracellular matrix organization; response to oxidative stress; blood coagulation
Cellular component: extracellular region; extracellular matrix
Genetic constraint (gnomAD): Loss-of-function variants: 37 observed, 39.54 expected, observed/expected ratio (o/e) 0.94, 90% interval 0.72 to 1.23. The upper end of that interval is the gene's LOEUF score, 1.23, which puts it in group 5 of 6, group 1 being the genes least tolerant of losing a copy. Missense variants: 427 observed, 460.72 expected, observed/expected ratio (o/e) 0.93, 90% interval 0.86 to 1. Synonymous variants: 166 observed, 172.45 expected, observed/expected ratio (o/e) 0.96, 90% interval 0.85 to 1.1.
Homologues: Orthologues: chimpanzee ANGPTL7 (99% identical), macaque ANGPTL7 (98% identical), dog ANGPTL7 (92% identical), pig ANGPTL7 (89% identical), rabbit ANGPTL7 (89% identical), rat Angptl7 (86% identical), mouse Angptl7 (86% identical), guinea pig ANGPTL7 (85% identical), tropical clawed frog angptl7 (72% identical), zebrafish angptl7 (64% identical). Paralogues in human: ANGPT2 (35% identical), ANGPT4 (35% identical), ANGPT1 (34% identical), TNR (32% identical), ANGPTL1 (31% identical), ANGPTL2 (31% identical), TNXB (31% identical), FGL1 (30% identical), FIBCD1 (30% identical), FCN2 (30% identical), FGB (30% identical), TNC (30% identical), and 13 more.
Diseases named in the same sentence as ANGPTL7 in open-access papers:
ANGPTL7 is named in the same sentence as 38 diseases in open-access papers, as found by Europe PMC text mining. Sharing a sentence is not in itself a finding about the gene and the disease. The quoted sentences say what the papers report.
glaucoma (11 papers, 2014 to 2025). Increased pressure in the eyeball due to obstruction of the outflow of aqueous humor. "A recent study found that ANGPTL7 protein-altering variants exert a strong protective effect on glaucoma and suggested ANGPTL7 as a therapeutic target for glaucoma." (PMID 35136015, 2022). "We further identify an ANGPTL7 missense variant in FinnGen cohort with more than 50-fold enrichment in the Finnish population that provides protection against glaucoma and its subtypes." (PMID 32369491, 2020). "Our genetic data from ANGPTL7 homozygotes with up to a 69% risk reduction for all glaucoma and 80% risk reduction for primary open-angle glaucoma suggest that this is likely to be a safe and effective strategy for therapeutic intervention." (PMID 32369491, 2020). "This additional ANGPTL7 association data, obtained in 6,537 glaucoma patients and 170,362 controls, provided strong support that protein-altering variants in ANGPTL7 protect against glaucoma (case definitions described in S7 Table)." (PMID 32369491, 2020). "Our results highlight the benefits of multi-cohort analysis for the discovery of rare protein-altering variants in common diseases and indicate ANGPTL7 as a therapeutic target for glaucoma." (PMID 32369491, 2020). "We discover an allelic series of multiple rare ANGPTL7 missense and nonsense variants in UK Biobank that lower intraocular pressure and reduces the risk of glaucoma." (PMID 32369491, 2020). "We then sought evidence from the FinnGen dataset that either the same or novel Finnish-enriched protein-altering variants would confirm the association of ANGPTL7 with protection from glaucoma." (PMID 32369491, 2020). "ANGPTL7 is highly expressed in ocular tissues (such as the trabecular meshwork), and is primarily involved in intraocular pressure regulation, extracellular matrix remodeling, and is closely associated with glaucoma, inflammation, and oxidative stress." (PMID 40901474, 2025). "In addition to being expressed in tissues directly relevant in glaucoma, several lines of evidence have implicated ANGPTL7 in glaucoma pathophysiology." (PMID 36192519, 2022). "The population cohorts from founder populations enable future recall studies focusing on individuals homozygous for the allele, which can eventually improve our understanding of the mechanism by which ANGPTL7 disruption leads to protection to glaucoma risk and lowering of IOP." (PMID 32369491, 2020). "Confirmation of an ANGPTL7 effect on glaucoma risk was seen in data from an independent Finnish-specific protein-altering missense substitution, p.Arg220Cys, which was strongly associated with protection from glaucoma (P = 2.0x10-12, OR = 0.71 [95% CI: 0.64–0.78], S7 Fig)." (PMID 32369491, 2020). "Additionally, future studies should assess whether ANGPTL7 variants modify the progression of glaucoma, for example, whether ANGPTL7 carriers are less likely to go from glaucoma diagnosis to potential surgery." (PMID 32369491, 2020). "Our study shows that imCSSC-derived EVs can specifically target ANGPTL7 expression, making them a promising preclinical therapy for glaucoma." (PMID 39847376, 2025). "–42 Elevated concentrations of the ANGPTL7 protein were observed in humous aqueous from patients with glaucoma." (PMID 39847376, 2025). "These discoveries shed novel light on the promoting role of ANGPTL7 in the development of glaucoma and present new targets for its treatment." (PMID 35136015, 2022). "It is imperative to elucidate the molecular mechanisms of ANGPTL7 that lead to glaucoma pathology and find new potential therapeutic targets." (PMID 35136015, 2022). "First, elevated levels of ANGPTL7 mRNA and protein were observed in eye tissues from glaucoma patients compared to controls, and under conditions of increased IOP simulated by perfusion of eye anterior segment explants." (PMID 36192519, 2022).
glaucoma (continued). "We report the identification and functional characterization of rare coding variants (including loss-of-function variants) in ANGPTL7 associated with reduction in IOP and glaucoma protection." (PMID 36192519, 2022). "Rare variant association data from human genetics combined with in vitro and in vivo functional validation highlight ANGPTL7 as a promising therapeutic target for intraocular pressure reduction, and protection from glaucoma." (PMID 36192519, 2022). "Future studies will explore the possibility of regulating the SP1/ANGPTL7/ROCK axis as targeted therapies for steroid-induced glaucoma and POAG." (PMID 35136015, 2022). "While our genetic discovery provides compelling evidence of involvement of ANGPTL7 in glaucoma, several important questions remain to be answered before its eventual clinical translation." (PMID 32369491, 2020). "In the context of the other established variants in glaucoma, including the protein-truncating variants in MYOC, p.Gln175His and the 57-fold Finnish-enriched p.Arg220Cys variants in ANGPTL7 exert a comparable protective effect." (PMID 32369491, 2020). "Our results support inhibition or down-regulation of ANGPTL7 as a therapeutic strategy for glaucoma." (PMID 32369491, 2020). "The multi-cohort allelic series analysis of protein-altering variants in ANGPTL7 in a total of 10,806 glaucoma patients and over 400,000 controls identifies a significant lowering effect on IOP and protective association with glaucoma." (PMID 32369491, 2020). "The biological role of ANGPTL7 is yet to be understood except for a recently proposed role in the pathophysiology of glaucoma." (PMID 28264047, 2017). "Studies in patients with glaucoma, a condition characterised by increased intraocular pressure, have reported elevated Angptl7 expression in the cornea." (PMID 25259444, 2014). "Due to its role in extracellular matrix formation of trabecular meshwork of the eye, a role of ANGPTL7 in glaucoma was assumed." (PMID 25409434, 2014). "Additionally, in a glaucoma model, ANGPTL7 promotes oxidative stress and mitochondrial dysfunction, while inhibiting its expression can alleviate oxidative damage." (PMID 40901474, 2025). "Based on this, we could extend the siRNA knockdown findings to humans and surmise that inhibition of ANGPTL7 in adulthood could be an efficacious strategy to lower IOP and, eventually, the risk for glaucoma." (PMID 36192519, 2022). "Indeed, the concentration of ANGPTL7 protein was found to be elevated in aqueous humor from patients with glaucoma." (PMID 24478758, 2014). "Recently, a functional role for ANGPTL7 has been proposed in the pathophysiology of glaucoma." (PMID 24478758, 2014). "Together, these new analyses provide further support for the role of ANGPTL7 in IOP regulation and glaucoma pathogenesis." (PMID 36192519, 2022). "This study contributes to revealing the molecular mechanisms of ANGPTL7 in CLAN formation, which is involved in TM dysfunction and glaucoma pathogenesis." (PMID 35136015, 2022). "In this study, we present genetic and functional evidence for a role for ANGPTL7 in the physiological control of IOP and as a potential target for glaucoma therapy." (PMID 36192519, 2022). "Given the Finnish enrichment of the known strong glaucoma risk allele, p.Gln368Ter, in MYOC (MAF in Finland = 0.3%, MAF in Non-Finnish European = 0.16%, reference sequence: NM_00026), we next asked whether carriers have risk reduced if they carry ANGPTL7 p.Arg220Cys." (PMID 32369491, 2020). "Collectively, our data suggest that ANGPTL7 is important for IOP homeostasis and is amenable to therapeutic modulation to help maintain a healthy IOP that can prevent onset or slow the progression of glaucoma." (PMID 36192519, 2022). "Though ANGPTL7 has been extensively studied, its potential functions in glaucoma have not been characterized." (PMID 35136015, 2022).
glaucoma (continued). "Our results establish an important role for ANGPTL7 as a physiological regulator of IOP and suggest that it is also amenable to modification by pharmacological tools, making it a compelling target for a glaucoma therapeutic." (PMID 36192519, 2022). "This study shows that ANGPTL7 transcriptionally regulated by SP1 can modulate CLAN formation via the RhoA/ROCK pathway and provides novel insights into how the TM ultrastructure and functions may be altered in some types of glaucoma." (PMID 35136015, 2022).
Obesity (6 papers, 2017 to 2025). Accumulation of substantial excess body fat. "To better understand the role of ANGPTL7 in obesity we looked at its association with lipid profile." (PMID 28264047, 2017). "This study was designed to study the expression level of ANGPTL7 in circulation and in subcutaneous adipose tissue at the mRNA and protein levels and to study the effect of physical exercise on its expression level as well as its association with clinical markers of obesity." (PMID 28264047, 2017). "While our MR results suggest that increased protein levels are associated with decreased BMI, one small observational study finds the opposite result, where ANGPTL7 is increased in subjects with obesity." (PMID 37550624, 2023). "In this study elevated levels of ANGPTL7 in patients with obesity and OSA were found, which decreased after bariatric surgery." (PMID 36017324, 2022). "A previous study examined angiopoietin-like protein 7 (ANGPTL7) levels in obesity and the effect of physical activity on its expression level." (PMID 36017324, 2022). "In agreement with the previously reported positive correlation between ANGPTL7 and TG in individuals with obesity, we find ANGPTL7 to have a significant positive correlation with TG in individuals diagnosed with OSA." (PMID 36017324, 2022). "In conclusion, our data shows for the first time that obesity increases the level of ANGPTL7 in both plasma and adipose tissue." (PMID 28264047, 2017). "This study was designed to shed light on the function of ANGPTL7 in obesity and its modulation by physical exercise as well as its potential association with lipid profile." (PMID 28264047, 2017). "Collectively, our data shed the light on the expression pattern of ANGPTL7 in obesity and its potential role in TG metabolism as well as the benefit of exercise in reducing its level in obese subjects." (PMID 28264047, 2017). "ANGPTL7 level was also increased after palmitate treatment in vitro further supporting its role in obesity." (PMID 28264047, 2017). "In order to mimic obesity conditions to test ANGPTL7 level in vitro, HepG2 and 3T3-L1 cells were treated with palmitate." (PMID 28264047, 2017). "In conclusion, we have demonstrated for the first time that the expression of ANGPTL7 is increased in obesity in circulation as well as in adipose tissue." (PMID 28264047, 2017). "Moreover, ANGPTL7 seemed to have relavence to high-risk factors of atherosclerosis and CHD such as inflammation, endothelial cell injury, obesity and diabetes." (PMID 41143193, 2025). "A previous study demonstrated that people with obesity had an increased expression of ANGPTL7." (PMID 36017324, 2022). "From a biomarker perspective we have also identified several genes elevated in IMF that encode proteins that have been connected to human obesity and potentially could be detectable in the plasma; these include INHBA and ANGPTL7." (PMID 31992204, 2020). "A recent conference abstract was also published showing increased ANGPTL7 level in obesity." (PMID 28264047, 2017). "Taken together, ANGPTL7 might constitute another target for obesity therapeutic drugs that can be further studied to better understand its role in lipid metabolism and other metabolic pathways." (PMID 28264047, 2017). "Even though other ANGPTL proteins family members have been implicated in obesity, insulin resistance and diabetes, no studies have looked at the role of ANGPTL7 under these conditions." (PMID 28264047, 2017). "The relation between ANGPTL7 and TG alludes to a role for ANGTPL7 in regulating TG metabolism in obesity, which was supported by the increase in ANGPTL7 expression after palmitate treatment (saturated fatty acid) in an in vitro setup." (PMID 36017324, 2022). "Although it has been proposed that ANGPTL7 levels are increased in obesity (and reduced after physical exercise), we do not observe any evidence of genetic association in either UK Biobank or FinnGen to support this hypothesis." (PMID 32369491, 2020).
breast carcinoma (5 papers, 2014 to 2023). "As another mechanism underlining nifedipine promoting the breast cancer cell migration, up-regulation of ANGPTL7 was found in response to the nifedipine treatment." (PMID 25436889, 2014). "However, reduced expression of ANGPTL7 at the distant sites’ is significantly higher than the normal spine, bone, and lung endogenous tissue-specific expression, suggesting truncated expression ANGPTL7 are linked to breast cancer metastasis." (PMID 34072157, 2021). "Prior studies have revealed striking ANGPTL7 underexpression in various cancers such as colorectal cancer and breast cancer." (PMID 34026765, 2021). "Although ANGPTL7 is overexpressed in breast cancer, the role of ANGPTL7 in breast cancer progression and metastasis is still unclear." (PMID 34072157, 2021). "ANGPTL7 (angiopoietin-like protein 7) is a new pro-angiogenetic factor, which is highly expressed in colorectal, ovary, and breast cancer." (PMID 34447410, 2021). "However, the HR for OS with the ANGPTL7 expression was 0.657 (95% CI = 0.529–0.816; p < 0.001) for the SACN-B cohort, suggesting breast cancer patients with a high ANGPTL7 expression score have better survival." (PMID 34072157, 2021). "Interestingly, primary tumor expressing ANGPTL7, MMP3, LCN2, S100A8, and ESM-1 levels that were upregulated in 4T1.2 cells was strongly associated with breast cancer patients’ survival outcomes." (PMID 34072157, 2021).
colorectal cancer (4 papers, 2021 to 2025). A primary or metastatic malignant neoplasm that affects the colon or rectum. "Experimental evidence supports that angiopoietin-like 7 (ANGPTL7) plays a role in proangiogenesis and vascularization in colorectal cancer, and this process is partially associated with exosomes." (PMID 38341827, 2024). "The higher expression level of ANGPTL7 was also observed in colorectal cancer based on the gene profile analysis." (PMID 34291083, 2021).
diabetes (3 papers, 2016 to 2025). "A recent mechanistic study reported that overexpression of ANGPTL7 could upregulate SOCS3, which inhibited the phosphorylation of AKT, promoted ERK1/2 phosphorylation and ultimately led to insulin resistance and type 2 diabetic mellitus (T2DM) in mouse." (PMID 36078120, 2022).
Insulin resistance (3 papers, 2022 to 2024). Increased resistance towards insulin, that is, diminished effectiveness of insulin in reducing blood glucose levels. "Overexpression of Angptl7 in healthy mice can also lead to insulin resistance-like characteristics, resulting in inhibited glucose uptake and insulin signal pathway." (PMID 38714962, 2024). "In a recent study, Xu and colleagues demonstrated ANGPTL7 as a potential therapeutic target for the treatment of insulin resistance and type 2 diabetes (T2D)." (PMID 36017324, 2022). "Meanwhile, we identified a population of ANGPTL7+ fibroblasts (FBs), which may be profibrotic and involved in insulin resistance in human GSVs." (PMID 36078120, 2022). "ANGPTL7 was found to play a critical role in inducing insulin resistance, which occurred through multiple mechanisms involving the down regulation of Insulin receptor (INSR), upregulation of suppressor of cytokine signaling 3 protein (SOCS3) to degrade insulin receptor substrate 1 (IRS1)." (PMID 36017324, 2022). "Because of its role in inflammation, insulin resistance and T2D we hypothesized that ANGPTL7 expression level might be affected by OSA." (PMID 36017324, 2022).
lung carcinoma (3 papers, 2015 to 2021). "ANGPTL7 was overexpressed in colon cancer and, more rarely, in breast and ovary cancers, while it seemed to be expressed at basal level in prostate and lung cancer." (PMID 29389861, 2018). "A recent study demonstrated that ANGPTL7 was overexpressed in colon cancer and, more rarely, in breast and ovary cancers, while it seemed to be expressed at basal level in prostate and lung cancer; moreover, the protein was overexpressed in liver metastasis from CRC." (PMID 29389861, 2018). "Further study will be necessary to determine whether other ANGPTLs, such as ANGPTL1, ANGPTL5, ANGPTL7, also enhance metastasis in lung cancer." (PMID 26056041, 2015). "As AGER and ANGPTL7 both show strong links to cancer, it is plausible that their interacted gene ATP13A4-AS1 also engages in the progression of lung cancer by exerting similar impacts on cellular activities." (PMID 34026765, 2021).
ovarian cancer (3 papers, 2018 to 2022). A primary or metastatic malignant neoplasm involving the ovary. "For example, exosomal angiopoietin-like protein 7 (ANGPTL7) secreted by the human ovarian cancer cells can promote tumor angiogenesis by regulating glucose and lipid metabolism, and oxidative stress." (PMID 36588730, 2022). "Studies have found that ANGPTL7 is over-expressed in colon cancer and less frequently so in ovarian cancer and expressed at a basal level in prostate cancer and lung cancer." (PMID 35962042, 2022).